NINJ1 (ninjurin 1)
Diseases named in the same sentence as NINJ1 in open-access papers (continued):
Sharing a sentence is not in itself a finding about the gene and the disease.
diabetes (7 papers, 2019 to 2025). "Meanwhile, the crucial role of NINJ1 in cardiovascular diseases, diabetes, inflammation, and cancer has also been elucidated." (PMID 39958360, 2025). "Our findings align with reports of Ninj1-mediated endothelial dysfunction in multiple sclerosis and diabetes, supporting the concept of context-dependent Ninj1 function across diseases and cellular environments." (PMID 41280941, 2025). "Recently it has been reported that Ninj1 is significantly upregulated in diabetes patients, and that functional blocking of Ninj1 attenuates IL-6 and MCP-1 overexpression and protects vascular defects." (PMID 33924583, 2021). "NINJ1 was involved in endothelial dysfunction and inhibition of NINJ1 expression was a potential therapeutic strategy to prevent endothelial dysfunction in diabetes." (PMID 37858098, 2023). "In this study, we investigated the role of Ninj1 in physiological (postnatal vessel formation) and pathological (endotoxin-mediated inflammation and diabetes) conditions and developed a strategy to regulate Ninj1 using specific micro (mi)RNAs under pathological conditions." (PMID 34974535, 2022). "Thus, further studies are warranted to verify the pharmacological relevance of phaseolin in regulating the activation and recruitment of macrophages mediated by Ninj1 in inflammatory diseases such as diabetes." (PMID 33924583, 2021). "Therefore, an investigation into the precise role of NINJ1 in bone homeostasis in metabolic diseases such as diabetes might yield new insights into the systemic regulation of bone metabolism." (PMID 30700695, 2019). "As expected, miRNA-125a-5p inhibited the expression of Ninj1 and Cl-cas3, reduced expression of inflammatory cytokines and significantly reduced the leakage of FITC-dextran in STZ-induced diabetes in ICR mice." (PMID 34974535, 2022). "Pericytes are known to gradually disappear as diabetes develops, and we could not detect pericytes expressing Ninj1 in DR." (PMID 34974535, 2022).
multiple sclerosis (7 papers, 2020 to 2026). A progressive autoimmune disorder affecting the central nervous system resulting in demyelination. "Nerve Injury-Induced Protein 1 (Ninjurin-1) is an adhesion molecule implicated in inflammation and tissue injury, yet its role in neuroinflammatory diseases such as multiple sclerosis (MS) remains poorly defined." (PMID 42064092, 2026). "Animal studies demonstrate that Ninj1 inhibition through genetic knockout or monoclonal antibodies can mitigate tissue damage and inflammation in models of pulmonary fibrosis, multiple sclerosis, and liver injury." (PMID 41280941, 2025). "The NINJ1 gene produces a protein that is a homophilic cell adhesion molecule and plays a role in the progression of multiple sclerosis." (PMID 33670198, 2021). "Additionally, Ninj1 mediates macrophages recruitment in multiple sclerosis (MS)." (PMID 34974535, 2022).
colitis (5 papers, 2020 to 2025). Inflammation of the colon. "In a colitis-associated colorectal cancer mouse model, NINJ1 deficiency reduced inflammation and tumor development, with sex-specific effects linked to testosterone, emphasizing the importance of sex differences in its role." (PMID 40075648, 2025). "To confirm that Ninj1 in macrophages has an important function in colon inflammation, we generated mice with a myeloid cell-specific Ninj1 deficiency and studied the pathogenesis of colitis." (PMID 31963519, 2020). "Furthermore, mice harboring Ninj1-deficient myeloid cells also exhibit decreased levels of inflammation against colitis." (PMID 31963519, 2020). "We observed that loss of Ninj1 alleviates experimental colitis." (PMID 31963519, 2020). "In conclusion, our results demonstrate that Ninj1 in macrophages contributes to intestinal inflammation in experimental colitis." (PMID 31963519, 2020). "The tissue phenotypes associated with colitis were also quantified, and results reveal reduced colitis incidence in DSS-treated Ninj1 KO mice." (PMID 31963519, 2020). "The mRNA expressions of IL1β and IL6 were dramatically reduced by inhibiting Ninj1 with the blocking peptide during the development of colitis." (PMID 31963519, 2020). "We therefore investigated alteration of Ninj1 expression in macrophages during development of experimental colitis." (PMID 31963519, 2020). "Ki-67 and Alcian blue staining were performed to confirm the severity of colitis incidence in Ninj1 KO mice." (PMID 31963519, 2020). "Our results suggest that macrophages are responsible for expressing Ninj1 in colon tissues, which exhibit increased Ninj1 during colitis." (PMID 31963519, 2020). "Collectively, our results indicate that Ninj1 expression contributes to the activation of macrophages, thereby eliciting a pro-inflammatory response during colitis." (PMID 31963519, 2020). "To verify this result, we administered LPS to WT and Ninj1 KO Raw 264.7 to mimic macrophage activation during development of colitis." (PMID 31963519, 2020). "The results of this study illustrate that Ninj1 in macrophages is a regulatory factor involved in the development of colitis." (PMID 31963519, 2020). "Taken together, these results indicate that Ninj1 aggravates experimental colitis." (PMID 31963519, 2020). "Moreover, mice with conditional deletion of Ninj1 in myeloid cells (Ninj1fl/fl; Lyz-Cre+) alleviated experimental colitis compared with wild-type mice." (PMID 31963519, 2020). "Therefore, we propose that targeting Ninj1 may be a promising therapeutic approach to decreasing the pathogenesis of colitis." (PMID 31963519, 2020). "Notably, NINJ1 deficiency enhances lung cancer cell motility by upregulating ICAM-1 through the IL-6/STAT3 signaling pathway, while its overexpression suppresses colitis-mediated colon cancer growth by inhibiting macrophage migration and invasion via the repression of FAK signaling." (PMID 40075648, 2025). "Since Ninj1 is reported to play a crucial role in immune responses, we analyzed the expression of Ninj1 genes in an IBD patient cohort and in a mouse model of colitis." (PMID 31963519, 2020). "Furthermore, the results of our conventional KO study concurred with those of a previous study on the role of Ninj1 in DSS‐induced colitis, which demonstrated that Ninj1 in macrophages contributes to colitis by increasing pro‐inflammatory cytokine expressions." (PMID 36071453, 2022). "Although macrophage infiltration is shown to be a critical step in the development of colitis, there were no changes in the numbers of macrophages extracted from colons of DSS-treated WT and Ninj1 KO mice." (PMID 31963519, 2020).
endothelial dysfunction (4 papers, 2023 to 2026). In vascular diseases, endothelial dysfunction is a systemic pathological state of the endothelium (the inner lining of blood vessels) and can be broadly defined as an imbalance between vasodilating and vasoconstricting substances produced by (or acting on) the endothelium. "By contributing to endothelial dysfunction and vascular inflammation, Ninj1 emerges as a promising, targetable mediator of early atherogenesis." (PMID 41280941, 2025). "This may be because NINJ1 promotes the adhesion of monocytes and macrophages to endothelial cells, leading to endothelial dysfunction." (PMID 40356625, 2025). "Endothelial Ninj1 silencing was performed to assess its effects on NF-κB signaling, CXCL-8 expression, and ox-LDL-induced endothelial dysfunction." (PMID 41280941, 2025). "Ninj1 silencing in endothelial cells suppressed NF-κB signaling and its key inflammatory mediator CXCL-8, conferring protection against ox-LDL-induced endothelial dysfunction by enhancing proliferation and migration while reducing apoptosis (all p < 0.05)." (PMID 41280941, 2025).
hepatocellular carcinoma (4 papers, 2022 to 2025). A malignant tumor that arises from hepatocytes. "Furthermore, elevated Ninj1 expression was observed in human hepatocellular carcinoma associated with cirrhosis and viral hepatitis, implying that Ninj1 might have potential roles in hepatic diseases." (PMID 36071453, 2022). "Although the hepatic upregulation of Ninj1 has been reported in human hepatocellular carcinoma and septic mice, little is known of its function during the pathogenesis of liver diseases." (PMID 36071453, 2022). "Furthermore, NINJ1 has been identified as a novel prognostic and severity predictor in human hepatocellular carcinoma, serous ovarian cancer, and retroperitoneal liposarcoma." (PMID 39958360, 2025). "Furthermore, NINJ1 is overexpressed in certain cancers, including hepatocellular carcinoma and acute lymphoblastic B-cell leukemia, highlighting its diagnostic potential." (PMID 40075648, 2025). "Additionally, NINJ1 is overexpressed in various cancers, such as hepatocellular carcinoma, acute lymphoblastic B-cell leukemia, urothelial bladder cancer, and circulating prostate cancer cells." (PMID 39958360, 2025). "Moreover, the expression of NINJ1 promoted p21 levels and G1 cell cycle arrest in Huh-7 hepatoma cells, and NINJ1-overexpressed cells showed increased SAβG activity, suggesting the vital role of NINJ1 in cellular senescence regulation." (PMID 38062164, 2024). "The liver is one of the organs that express Ninj1, and the upregulation of Ninj1 in liver has been reported in human hepatocellular carcinoma and septic mice, which suggests Ninj1 may play roles in the pathogenesis of hepatic diseases." (PMID 36071453, 2022).
lung cancer (4 papers, 2020 to 2025). A malignant neoplasm involving the lung. "Nerve injury-induced protein 1 (Ninjurin1, Ninj1) has been implicated in lung cancer; however, the pathological role of Ninj1 in the context of lung tumorigenesis remains largely unknown." (PMID 35395804, 2022). "Additionally, NINJ1 inhibits the IL-6 signaling pathway both in vitro and in vivo, suppressing lung cancer migration, invasion, and metastasis." (PMID 39980566, 2025). "Ninj1-mediated Wnt/β-catenin signaling is further enhanced by the addition of exogenous Wnt3a, a Wnt ligand that activates the canonical Wnt signaling pathway and promotes lung cancer progression." (PMID 35395804, 2022).
breast carcinoma (3 papers, 2024 to 2025). "Supporting clinical relevance, high FGD3 expression strongly correlated with improved relapse-free survival in breast cancer patients after chemotherapy and this correlation was stronger than was seen for NINJ1 and other proteins associated with lytic cell death." (PMID 41225536, 2025). "Although the correlation between NINJ1 level in breast cancer and chemotherapy response was much weaker than that of FGD3, it was nonetheless significant." (PMID 41225536, 2025). "Despite their important roles in specific types of lytic cell death, at least in these unstratified breast cancer patients, NINJ1, GSDMD and MLKL showed much lower correlation with overall response to chemotherapy." (PMID 41225536, 2025). "In the current study, we generated several peptides derived from the N-terminus of NINJ1 and NINJ2 and showed that peptides targeting cell adhesion or the NINJ1-NINJ2 complex can elicit growth suppression in breast cancer cells." (PMID 40136650, 2025). "We also validated the ferroptosis-protective effects of NINJ1 knockdown in additional cancer cell types, including—MDA-MB-231 (breast cancer) and PC3 cells (prostate cancer)." (PMID 39424803, 2024). "Since both NINJ1 and NINJ2 are found to be over-expressed in several types of cancer, including breast cancer, targeting their interaction may be a feasible approach for cancer therapeutic development." (PMID 40136650, 2025). "Given that a role for NINJ1 in response to membrane stretch was identified very recently, this suggested that NINJ1 might impact the response to cell swelling induced by chemotherapy agents, extending the potential role of NINJ1 in PMR from inflammation in macrophage to breast cancer." (PMID 41225536, 2025).
colon cancer (3 papers, 2020 to 2024). "Given the general role of the Wnt/β-catenin signaling pathway in human cancers, we assessed the pathological role of Ninj1 in histologically distinct epithelial tumors, including breast and colon cancers." (PMID 35395804, 2022). "During colon cancer development, overexpression of Ninj1 suppresses the migration of macrophages, resulting in the alleviation of cancer development." (PMID 31963519, 2020). "Similar to the previous paper that analyzed the role of Ninj1 in colon cancer, several reports have demonstrated that Ninj1 mediates migration of cells in inflammatory conditions." (PMID 31963519, 2020). "In this paper, we present the different roles of Ninj1 in macrophages under intestinal inflammatory conditions as compared with TAM during colon cancer development." (PMID 31963519, 2020). "Moreover, we analyzed previously published mRNA profiles and determined that Ninj1 expression is not induced in colon cancer tissues of mice, as compared to mice with normal colons (GSE31106)." (PMID 31963519, 2020).
Hepatitis (3 papers, 2022 to 2025). Inflammation of the liver. "Initially, we observed that loss of Ninj1 attenuated LPS/D‐gal‐induced hepatitis in Ninj1‐deficient mice." (PMID 36071453, 2022). "Before investigating whether Ninj1 is associated with the development of hepatitis, we confirmed the expression pattern of Ninj1 in normal liver tissue." (PMID 36071453, 2022). "Hepatitis‐induced Ninj1 KO mice tended to have lower ALT and AST levels than WT mice, but this was not significant." (PMID 36071453, 2022). "On the other hand, exposure to LPS/D‐gal for 5 h induced severe hepatic inflammation in WT mice, but interestingly, Ninj1 KO mice showed milder hepatitis than WT mice." (PMID 36071453, 2022). "WT mice (Ninj1+/+; Lyz2‐Cre/+) and myeloid‐specific Ninj1 KO mice (Ninj1floxed/floxed; Lyz2‐Cre/+) were subjected to LPS/D‐gal‐induced hepatitis." (PMID 36071453, 2022). "We then investigated Ninj1 expressions using GEO public data sets obtained from mice with experimental hepatitis and human ALF or alcoholic hepatitis patients." (PMID 36071453, 2022). "Since Ninj1 KO in myeloid cells did not attenuate hepatitis caused by LPS/D‐gal, we investigated whether loss of Ninj1 influences TNF‐α‐induced hepatocyte death." (PMID 36071453, 2022). "Taken together, these results suggest macrophage Ninj1 does not play a crucial role in the pathogenesis of LPS/D‐gal‐induced hepatitis and that TNF‐α release by macrophages is not a primary factor of the phenotype of conventional Ninj1 KO mice." (PMID 36071453, 2022).
injury (3 papers, 2017 to 2024). Damage inflicted on the body as the direct or indirect result of an external force, with or without disruption of structural continuity. "NijA is part of a conserved family of homophilic cell-adhesion molecules, of which the first identified member, Nerve injury-induced protein 1 (Ninjurin 1, Ninj1) was detected as a factor upregulated after nerve injury in rodents." (PMID 39545919, 2024). "The nerve injury‒induced protein, Ninjurin-1 (Ninj1), a cell surface adhesion molecule with homophilic binding activity, was originally identified as a protein that gets expressed in peripheral nerve tissues in response to nerve injury." (PMID 36262667, 2022).
Acute hepatitis (2 papers, 2022 to 2023). Acute hepatic injury resulting from inflammation typically accompanied by increased serum alanine transaminase activity. "A recently reported NINJ1-neutralizing monoclonal antibody that hindered the formation of NINJ1 polymers and effectively reduced liver injury in mouse models of acute hepatitis highlights the potential therapeutic value of neutralizing NINJ1 activity." (PMID 37939552, 2023). "In this work, we investigated whether Ninj1 plays a crucial role in liver inflammation using an LPS/D‐gal‐induced acute hepatitis murine model." (PMID 36071453, 2022). "Based on our observation that serum TNF‐α levels of Ninj1 conventional KO mice were lower than those of WT mice after 5 h of LPS/D‐gal treatment, we supposed lack of Ninj1 in myeloid‐lineage cells, including macrophages, had attenuated the severity of acute hepatitis by reducing TNF‐α production." (PMID 36071453, 2022).
acute liver failure (2 papers, 2022 to 2023). Rapid deterioration of liver function causing encephalopathy and coagulopathy. "NINJ1 deficiency also alleviated LPS/D-galactosamine-induced acute liver failure by reducing TNF-α-induced hepatocyte apoptosis." (PMID 36835580, 2023). "In the present study, the role of Ninj1 in liver inflammation was explored using lipopolysaccharide (LPS)/D‐galactosamine (D‐gal)‐induced acute liver failure (ALF) model." (PMID 36071453, 2022).
COVID-19 (2 papers, 2022 to 2025). A disease caused by infection with severe acute respiratory syndrome coronavirus 2. "Our study provides insight into the correlation between NINJ1 and the disease progression of influenza and COVID-19, as well as the mechanism underlying how NINJ1 functions during IAV-induced PANoptosis." (PMID 40983621, 2025). "Through scRNA-seq analysis, we associated the expression level of NINJ1 in macrophages with the severity and prognosis of influenza and COVID-19." (PMID 40983621, 2025). "Furthermore, we extend our conclusion to COVID-19 and reveal an association of NINJ1 expression in monocytes and macrophages with disease prognosis and inflammatory responses." (PMID 40983621, 2025). "Furthermore, we revealed an association between NINJ1 upregulation and poor outcomes in patients with COVID-19." (PMID 40983621, 2025). "Since influenza and COVID-19 share many similarities in terms of virology and pathophysiology, we sought to verify the role of NINJ1 in COVID-19 patients." (PMID 40983621, 2025). "Collectively, our scRNA-seq analysis reveals the potential of NINJ1 in Mo/Mas to be a biomarker of hyperinflammation status and poor prognosis in patients with severe COVID-19." (PMID 40983621, 2025). "In line with our results, the expression of NINJ1 was aberrantly increased in Mo/Mas from deceased COVID-19 patients." (PMID 40983621, 2025).
diabetic retinopathy (2 papers, 2022 to 2025). "Taken together, these findings suggest that Ninj1 plays a pivotal role in macrophage-mediated vascular integrity and that miR-125a-5p acts as a novel regulator of Ninj1 in the management of inflammatory diseases and diabetic retinopathy." (PMID 34974535, 2022).
experimental autoimmune encephalomyelitis (2 papers, 2021 to 2024). An autoimmune demyelinating disease of the central nervous system that is produced experimentally in animals by the injection of homogenized brain or spinal cord in Freund's adjuvant. "A similar homing function for Ninj1 in mammalian leukocytes has been demonstrated in experimental autoimmune encephalomyelitis models, where increased Ninj1 expression in T cells in the lung facilitates their subsequent migration to the CNS." (PMID 39545919, 2024).
ischemia (2 papers, 2024 to 2025). A hypoperfusion of the BLOOD through an organ or tissue caused by a PATHOLOGIC CONSTRICTION or obstruction of its BLOOD VESSELS, or an absence of BLOOD CIRCULATION. "Similarly, in response to ischemia, NINJ1 enhanced the formation of functional matured vessels through the association between pericytes and ECs, resulting in blood flow recovery from ischemia." (PMID 39958360, 2025).